IGF1R (insulin like growth factor 1 receptor)
Diseases named in the same sentence as IGF1R in open-access papers (continued):
Sharing a sentence is not in itself a finding about the gene and the disease.
meningioma (10 papers, 2013 to 2026). A generally slow growing tumor attached to the dura mater. "Inhibition of the miR-483/IGF-2 pathway with miR-483 oligonucleotide inhibitor, anti-IGF-2 neutralizing antibodies, and IGF1R small molecule tyrosine kinase inhibitors caused rapid loss of viability of cultured meningioma tumor-derived cells." (PMID 36809604, 2023). "Importantly, blockade of the IGF-2 receptor (IGF1R) tyrosine kinase inhibitor with a small molecule inhibitor resulted in a rapid loss of viability of cultured meningioma cells." (PMID 38577017, 2024). "Dual blockade of mTORC1/2 and IGF1R/insulin signaling effectively reduced pAkt T308 and cell viability, supporting co-inhibition as a potential therapeutic strategy in NF2-deficient meningiomas." (PMID 41200151, 2025). "The observed inhibitory effects of GSK1838705 A and ceritinib on IGF1R, combined with pharmacokinetic data, suggest potential in vivo applications as novel treatments for meningioma." (PMID 38577017, 2024). "Inhibition of miR-483–5p, anti-IGF-2 neutralizing antibodies, and small molecule tyrosine kinase inhibitors targeting IGF1R have demonstrated efficacy in limiting meningioma cell proliferation in vitro." (PMID 38577017, 2024). "miRNA modulation, anti-IGF-2 neutralizing antibodies, and inhibitors against IGF1R were evaluated in a tumor-derived primary cultures of meningioma cells." (PMID 36809604, 2023). "IGF-2-mediated Akt phosphorylation was also strongly blocked by GSK1838705A, ceritinib and linsitinib suggesting that the mechanism by which these drugs inhibit meningioma cell growth is mainly via IGF1R blockade." (PMID 36809604, 2023). "Despite the lack of efficacy observed in high grade cancers, our data suggests that IGF1R blockade has promise in meningioma treatment, given meningioma’s apparent high dependence on the IGF-2 pathway." (PMID 36809604, 2023). "Genes involved in tumor metabolism, like IGF1R, are also differentially expressed in meningioma subgroups with higher rates of membrane turnover, higher energy demand and increased resistance to apoptosis." (PMID 23840654, 2013). "Genes involved in tumor metabolism, like IGF1R, are also differentially expressed in those meningioma subgroups with higher rates of membrane turnover, higher energy demand and increased resistance to apoptosis." (PMID 23840654, 2013). "In atypical meningioma, on the contrary, levels of IGF1R are similar to those detected in the benign meningioma subgroup with lower metabolic aggressiveness." (PMID 23840654, 2013). "IGF1R is over-expressed in the benign meningioma subgroup with higher rates of membrane turnover, higher energy demand and increased resistance to apoptosis." (PMID 23840654, 2013). "The real-time RT-PCR data confirmed significantly higher mRNA levels of IGF1R in benignB with respect benignA meningioma." (PMID 23840654, 2013). "Also, the combination more effectively blocked ligand-mediated phosphorylation of EGFR, ErbB3, and IGF-1R and elicited major changes in the expression of genes, including the upstream regulators of several signaling networks important for meningioma growth." (PMID 41417846, 2026). "Small molecule tyrosine kinase inhibitor blockade of the IGF-2 receptor (IGF1R) resulted in rapid loss of viability of cultured meningioma tumor-derived cells, suggesting that autocrine IGF-2 feedback is obligatory for meningioma tumor cell survival and growth." (PMID 36809604, 2023). "Meningioma tumor cells also express a high level of IGF1R, the main receptor for IGF-2." (PMID 36809604, 2023). "Finally, laboratory studies have confirmed that IGF1, IGF2, and IGF1R genes are overexpressed in meningioma." (PMID 24587258, 2014). "Indeed, sporadic reports have already suggested that inhibition of the IGF receptor (IGF-1R) could have a role in future meningioma treatment." (PMID 38632533, 2024).
meningioma (continued). "Moreover, the expression of IGF-1R and its’ impact on cellular proliferation have been shown to be significantly influenced by glycaemia levels in other malignancies, indicating that a similar process could be possible in meningiomas as well." (PMID 38632533, 2024). "Among the orally available IGF-1R inhibitors, GSK1838705A, ceritinib, and linsitinib strongly inhibited meningioma cell growth in our in vitro model." (PMID 36809604, 2023). "Taken together, our data indicate that IGF1R inhibitors, including GSK1838705A and ceritinib, should be evaluated in mouse meningioma models and in clinical trials." (PMID 36809604, 2023). "Our results by gene expression microarrays and real-time RT-PCR show that IGF1R is closely related to metabolic aggressiveness in histological benign meningioma but not in atypical meninhioma." (PMID 23840654, 2013). "The observed IGF1R-inhibitory IC50 for GSK1838705A and ceritinib in cell-based assays along with the available pharmacokinetics data predicted that effective drug concentration could be achieved in vivo as a new medical treatment of meningioma." (PMID 36809604, 2023).
psoriasis (10 papers, 2011 to 2026). An autoimmune condition characterized by red, well-delineated plaques with silvery scales that are usually on the extensor surfaces and scalp. "The IGF-1/IGF1R pathway is associated with numerous hyperplastic epidermal disorders, such as psoriasis." (PMID 35216228, 2022). "IGF-1R mRNA is an identified miR-99a target that is known to be involved in the pathogenesis of psoriasis." (PMID 25663868, 2015). "Since, IGF-1R has been known to be involved in the pathogenesis of psoriasis and upregulated in psoriasis, they studied the relationship between miR-99a and IGF-1R." (PMID 25628647, 2014). "Both these observations suggest that aberrant silencing of miRNAs takes part in the pathogenesis of psoriasis by allowing the un-controlled signaling of IL-22 and IGF1R, respectively." (PMID 25208211, 2014). "IGF-1R was shown to be up-regulated in psoriasis, specifically in the proliferating basal layer of psoriatic lesions." (PMID 21687694, 2011). "IGF-1R, which is involved in skin development and the pathogenesis of psoriasis, is a predicted target of hsa-miR-99a." (PMID 21687694, 2011). "We used bioinformatics tools to predict possible targets of hsa-miR-99a, and decided to focus on one predicted target, IGF-1R, that is known to be involved in the pathogenesis of psoriasis." (PMID 21687694, 2011). "Regarding miR-99a, which is downregulated in psoriasis, a functional role is emphasized in the downregulation of insulin-like growth factor 1 receptor (IGF1R) signaling, which is upregulated in psoriasis and is responsible for hyperkeratosis and epidermal hyperplasia." (PMID 39796035, 2024). "IGF-1R is known to be involved in the pathogenesis of psoriasis." (PMID 21687694, 2011). "Interestingly, miR-99a-overexpressing human keratinocyte cells showed slower proliferation as compared to the control cells suggesting that miR-99a may function in the development of psoriasis by targeting IGF-1R." (PMID 25628647, 2014). "The levels of fasting glucose, insulin, IGFBP3, and IGFBP6 were higher in patients with psoriasis, while the levels of IGF-1, IGF-1R, and IGBP4 were higher in controls." (PMID 41635444, 2026).
respiratory failure (10 papers, 2005 to 2024). The significant impairment of gas exchange within the lungs resulting in hypoxia, hypercarbia, or both, to the extent that organ tissue perfusion is severely compromised. "Mice with a deletion of the IGF-1r gene (IGF-1R−/−) died at birth due to severe respiratory failure and displayed severe growth deficiency." (PMID 34685644, 2021). "The findings that genetic deletion of Igf1r or Igf1 caused lethal respiratory failure at birth limited the study of the potential role of IGF1R signaling in the postnatal lung." (PMID 33591952, 2021). "Since complete inactivation of Igf-1r is lethal at birth due to respiratory failure, we combined a knockout allele (Igf-1r-) and a hypomorphic allele (Igf-1rneo) in order to generate viable mice with markedly reduced levels of IGF-1R." (PMID 15819984, 2005). "While skeletal muscle-specific IGF-1R null mice showed no altered body weight or muscle mass, the double knockout of IGF-1R and IR showed a marked decrease in skeletal muscle mass and fiber size and died earlier, likely due to respiratory failure." (PMID 39638246, 2024). "Igf1r knockout mutants die immediately after birth from respiratory failure with birth weights at 45% of normal, and double knockout embryos of Igf1r and Insr exhibit a 70% reduction in fetal weight when compared with WT littermates." (PMID 35921893, 2022). "Some null mutants for the IGF-1R gene die of respiratory failure at birth, and those that do survive exhibit a severe growth deficiency (45% normal size)." (PMID 35840554, 2022). "IGF1R null mice die at birth of respiratory failure and exhibit only 45% of the body weight of their wild-type littermates." (PMID 24422716, 2014). "In the knockout mice heterozygous for the IGF-I receptor (Igf1r+/-), significant lifespan extension was observed in female mice, whereas homozygous knockout mice died at birth, probably as a result of respiratory failure." (PMID 19412415, 2007). "Since IGF-1R null mutant mice die at birth from respiratory failure, we generated compound heterozygous mice harboring a hypomorphic (Igf-1rneo) allele and a knockout (Igf-1r-) allele." (PMID 15819984, 2005). "Since IGF-1R null mutant mice die at birth from respiratory failure, we generated compound heterozygous mice harboring a hypomorphic (Igf-1rneo) and a knockout (Igf-1r-) receptor allele." (PMID 15819984, 2005). "Similar to the poor survival and growth deficits in the Slc7a7-deficient mouse models, global Igf1−/− and Igf1r−/− mouse models with depleted circulating IGF-1 concentrations manifested early lethality (due to respiratory failure) and growth failure (27-60% of WT body weights)." (PMID 37486182, 2023). "This tissue is an important target of IGF-1, as mice lacking IGF-1R die of respiratory failure upon birth." (PMID 39638246, 2024).
chordoma (9 papers, 2016 to 2025). Chordomas are rare malignant tumors arising from embryonic remnants of the notochord in axial skeleton. "Type 1 insulin-like growth factor receptor (IGF-1R) expression has been detected in the plasma membrane and cytoplasm of chordoma cells and IGF-1R inhibition is considered a therapeutic target in chordoma." (PMID 38652222, 2024). "Emerging literature supports a relationship between IGF-1/IGF-1R expression and prognosis in chordomas." (PMID 32733369, 2020). "Clinical trials of IGF-1R inhibitors in chordoma have thus far comprised phase I studies of combined anti-IGF-1R/EGFR inhibition and suggest some efficacy to this approach." (PMID 32733369, 2020). "Linsitinib, an IGF-1R inhibitor, was assessed in two studies, and effectively controlled chordoma progression in combination with erlotinib." (PMID 30775316, 2019). "Similar variation in IGF-1R expression and subcellular localization was noted in 15 further cases of chordoma." (PMID 27200287, 2016). "To determine the extent to which these appearances are representative, we performed IGF-1R IHC on 15 additional chordoma cases, including 3 cases originating in the sacrococcygeal region and 12 cases arising in the brain." (PMID 27200287, 2016). "Activation of IGF-1R and INSR is reportedly detectable in ~40% of chordomas and is associated with significant reduction in disease-free survival." (PMID 27200287, 2016). "Previous studies implicated receptor tyrosine kinases, including epidermal growth factor receptor (EGFR) and type 1 insulin-like growth factor receptor (IGF-1R), in chordoma biology." (PMID 27200287, 2016). "Another receptor of the same family, the IGF1R was also found to be expressed by most chordomas." (PMID 33946484, 2021). "Activation of IGF-1R signaling may therefore contribute to chordoma growth or progression, presenting a potential new biomarker and targetable pathway." (PMID 32733369, 2020). "Second, studies of genetic alterations in chordoma identified mutation or loss of the cell cycle regulator CDKN2A, which is of interest since we identified CDKN2C and CDKN3 as hits in a screen for proteins whose depletion enhances sensitivity to IGF-1R inhibition." (PMID 27200287, 2016). "A comprehensive genomic and transcriptomic analyses identified the IGF1R/FGFR/EGFR and CDK4/6 pathways as treatment strategies for chordoma patients." (PMID 41442054, 2025). "The majority of chordoma samples studied were positive for both IGF-1 and IGF-1R; the level of IGF-1R staining correlated with tumor volume." (PMID 32733369, 2020). "We suggest that trials incorporating assessment of these parameters should evaluate the effects of combined IGF-1R/INSR and EGFR inhibition in patients with recurrent chordomas." (PMID 27200287, 2016). "Another IHC study detected IGF-1R, IGF-1, and IGF-2 in 76, 90, and 50% of chordomas, respectively, with one-third showing moderate to strong IGF-1R, as in our study, and a significant correlation between IGF-1R staining intensity and primary tumor volume." (PMID 27200287, 2016). "IGF signaling is also important in chordoma tumorigenesis, since IGF-1 and IGF-1R have been detected in 92 and 76% of chordoma tissues, and are absent in benign notochordal cell tumor and fetal notochord." (PMID 30775316, 2019). "Our micro-array data revealed that a large number of genes were differentially expressed in chordoma tissues, including EGFR, PDGFRβ, IGF-1R and MET etc., which have been identified to the potential therapeutic targets in chordoma with both clinical and molecular evidence." (PMID 29348851, 2017). "In summary, this exceptionally durable response suggests that there may be merit in evaluating combined IGF-1R/INSR and EGFR inhibition in patients with chordomas that recur following failure of local treatment." (PMID 27200287, 2016).
COVID-19 (9 papers, 2021 to 2023). A disease caused by infection with severe acute respiratory syndrome coronavirus 2. "IGF1R, which blocks IGF-1R attenuates lung damage and reduces the risk of death in patients with COVID-19-related ARDS." (PMID 36204652, 2022). "The predicted lncRNA NEAT1 -hsa-miR-214-5p/hsa-miR-7-5p-IGF1R network may reduce the risk of death from ARDS in COVID-19 patients." (PMID 36204652, 2022). "It has been hypothesized that the blockage of IGF-1R may mitigate lung injury and decrease the risk of death in patients with COVID-19-related adult respiratory distress syndrome (ARDS)." (PMID 34452353, 2021). "IGF1R was previously found in serum and plasma exosomes, and recently identified as a novel plasma biomarker to predict mortality in COVID-19 patients." (PMID 35688943, 2022). "IGF1R has also recently been defined by some studies as a novel biomarker for predicting mortality in severe COVID-19 patients." (PMID 35692833, 2022). "Research has indicated the upregulation of IGF-1 and IGF-1R in the lung tissues of patients with ARDS related to COVID-19." (PMID 34452353, 2021). "The upregulation of IGF-1 and IGF-1R has been observed in the lung tissues of patients with ARDS related to COVID-19." (PMID 34452353, 2021). "Higher serum levels of IGF1R correlate with COVID-19 mortality." (PMID 37239019, 2023). "Further, DTP-based retrieval of approved drugs showed that combination therapy with sorafenib, sunitinib, nintedanib (PDGFRB), sunitinib, nintedanib, ruxolitinib (JAK1), and ceritinib (IGF1R) could be helpful to diabetic COVID-19 patients." (PMID 34067609, 2021). "In this study, six co-upregulated genes, RPS7, IGF1R, DICER1, ERH, MCTS1, and TNPO1, and two co-downregulated genes, FLNA and PXN, were identified from COVID-19 and thrombosis datasets." (PMID 35692833, 2022). "Based on bioinformatics analysis and previous studies, this study identified hub genes (RPS7, IGF1R, DICER1, ERH, MCTS1, TNPO1, FLNA, and PXN) that may contribute to the evaluation and treatment of COVID-19 and thrombosis." (PMID 35692833, 2022). "In addition, IGF1R inhibitors, EGFR inhibitors, VEGFR inhibitors, and AKT inhibitors were among the compounds predicted to target COVID-19 PBMCs." (PMID 33782412, 2021).
liposarcoma (9 papers, 2014 to 2020). A usually painless malignant tumor that arises from adipose tissue. "Insulin-like growth factor 1 receptor (IGF1R) is expressed in a wide range of tumors including liposarcoma; and IGF1R signaling is crucial for tumor formation and survival of malignant cells." (PMID 27893412, 2017). "Based on these as well as mathematic modeling, we have carried out a successful preclinical study using CDK4 and IGF1R inhibitors in liposarcoma." (PMID 26887042, 2016). "Based on this study as well as mathematical modeling we have carried out a preclinical study successfully by using CDK4 and IGF1R inhibitors in liposarcoma." (PMID 26887042, 2016). "Of note we did see prolonged stable disease in 3 of 6 liposarcoma patients which is interesting as IGF-1R has been reported as a potential therapeutic target in liposarcomas." (PMID 24458261, 2014). "We investigated whether KL impacts the aggressiveness of liposarcomas, in which IGF-1R signaling is frequently upregulated." (PMID 30441794, 2018). "A recent study showed that the combination of IGF1R and CDK4 inhibitors synergistically reduced the cell proliferation of liposarcoma cells." (PMID 27893412, 2017). "While both liposarcoma cell lines (DDLS and LS141) showed high levels of IGF1-R expression, only MPNST cell line showed significant levels of PDGFRα expression." (PMID 26675259, 2016).
oral squamous cell carcinoma (9 papers, 2012 to 2022). "MVP and IGF-1R expression were related in oral squamous cell carcinoma and conferred reduced long-term survival in patients suffering from advanced stages of the disease." (PMID 22931894, 2012). "For example, resveratrol inhibits oral squamous cell carcinoma via induction of apoptosis and G2/M phase cell cycle arrest and inhibits human leiomyoma cell proliferation via crosstalk between integrin αvβ3 and insulin-like growth factor 1 receptor (IGF-1R)." (PMID 32530437, 2020). "Insulin-like growth factor (IGF) signaling is involved in oral squamous cell carcinoma (OSCC), but IGF-1 receptor (IGF-1R)-mediated intricate regulatory networks among molecular interactions and signalling path ways in OSCC remain unclear." (PMID 24810113, 2014).
rheumatoid arthritis (9 papers, 2017 to 2025). A chronic, systemic autoimmune disorder characterized by inflammation in the synovial membranes and articular surfaces. "Such a shift in the regulatory balance of T cells following IGF1R inhibition has been recognised in several autoimmune conditions including multiple sclerosis, rheumatoid arthritis and type I diabetes mellitus." (PMID 36105797, 2022). "Some other potential receptor candidates including an isoform of decorin involved in WAT expansion, tyrosine kinase-like orphan receptor-1 (ROR1) in 3T3-L1 cells, or insulin-like growth factor 1 receptor (IGF-1R) in fibroblasts from rheumatoid arthritis patients have also been described." (PMID 28490838, 2017). "According to the results of molecular docking, in the context of rheumatoid arthritis, phytocannabinoids may bind to important target proteins such as PIK3CA, AKT1, MAPK9, PRKCD, BRAF, IGF1R, and NOS3." (PMID 36983855, 2023).